ACTN4 (actinin alpha 4)
Diseases named in the same sentence as ACTN4 in open-access papers (continued):
Sharing a sentence is not in itself a finding about the gene and the disease.
cancer (continued). "Since ACTN4/Akt-induced EMT may cause the resistance of cancer cells to DNA-damaging drugs, it is tempting to speculate that this mechanism is responsible for the failure of genotoxic anti-cancer therapies." (PMID 31766144, 2019). "Therefore, there is a profound association between high ACTN4 expression and the migratory potential of tumor cells, although the data does vary between different studies of the same type of cancer." (PMID 31766144, 2019). "Investigation of splice isoforms, key post-translational modifications and factors, and into regulating ACTN4 expression, may reveal novel prognostic markers associated with certain cancer phenotypes." (PMID 31766144, 2019). "However, the following extensive evidence supporting the oncogenic potential of ACTN4 has been collected, and it is now firmly accepted that the over-expression of ACTN4 is associated with tumorigenesis in most types of cancer." (PMID 31766144, 2019). "ACTN4 has also been strongly associated with cancer metastatic ability." (PMID 27121206, 2016). "Therefore, the association of ACTN4 expression with tumorigenicity and cancer metastasis needs to be further investigated in the clinic." (PMID 25885339, 2015). "While its connection to blastocysts is also unclear at this point in time, ACTN4 has been detected in higher levels in cells with higher motility and may be linked to metastatic processes in cancer." (PMID 26288249, 2015). "We identified actinin-4, an actin-bundling protein encoded by ACTN4, as a biomarker that could be used to evaluate the invasion and metastasis capabilities of cancer cells." (PMID 24574362, 2014). "Despite the importance of ACTN4 in structural support in podocytes and cell mobility in cancer, the specificity and role of ACTN4 in nephron NaCl transport were previously unrecognized." (PMID 39446130, 2024). "Suppressing or targeting ACTN4 significantly hinders cancer cell development, acting therapeutically." (PMID 38739940, 2024). "The identification of ACTB, ACTN4, INF2, and MYL6 as DEDRGs that are implicated in both PD and various cancer types opens up exciting possibilities for developing novel therapeutic strategies for human patients." (PMID 39329952, 2024). "Accordingly, the expression of ACTN4 in carcinoma tissues was higher than that in adjacent tissues in patients with NSCLC, which was detected by immunohistochemistry (IHC) assay." (PMID 38764726, 2024). "Cancer stem cells expressing ACTN4 displayed heightened capabilities, including increased mammosphere formation and enhanced tumorigenesis in vivo." (PMID 38002335, 2023). "Increased ACTN4 expression is directly correlated with more advanced cancer stages, elevated incidence of metastasis, poor patient prognosis, and tumor chemoresistance." (PMID 38002335, 2023). "ACTN4 is an actin-binding protein involved in many cellular processes, including cancer development." (PMID 36476259, 2022). "In this review, we have outlined the circumstances under which adjuvant chemotherapy is beneficial in NSCLC and discussed the biological roles of ACTN4 related to cancer invasion and metastases." (PMID 36139525, 2022). "Further studies are needed to identify the molecular mechanisms of ACTN4 in cancer metastasis and invasion in more detail." (PMID 36139525, 2022). "ACTN4 gene amplification is determined by fluorescence in situ hybridization (FISH) in cancer tissues and has been shown to be a prognostic factor in several cancers." (PMID 36139525, 2022). "Alph-actinin-4 (ACTN4), an actin-binding protein, modulates actin filament flexibility to regulate migration, invasion, and metastasis of cancer cells." (PMID 33628783, 2021). "And the expression of linear ACTN4 in 20 pairs of BC and para-cancer tissues were detected by qRT-PCR, data showed that linear ACTN4 was highly expressed in BC tissues." (PMID 34116677, 2021). "Intriguingly, it has been reported that MTBP suppresses cancer metastasis partly via inhibition of ACTN4 function." (PMID 33809929, 2021).
cancer (continued). "ACTN4 is abundant in various cancers such as pancreatic, cervical, and melanoma cancers, and it is a known oncogene." (PMID 33363146, 2020). "As an actin-binding protein, ACTN4 can participate in regulating cell migration, invasion, and metastasis via regulating the actin filament flexibility at the leading edge of invading cancer cells." (PMID 32855746, 2020). "ACTN4-overexpressing cancer cells have the potential to metastasize, because the overexpression of ACTN4 protein in cancer cells can stimulate the dynamic reconstruction of the actin cytoskeleton." (PMID 32855746, 2020). "This is coherent with many studies that reported the overexpression of ACTN4 in diverse biological conditions including diseases (such as cancers) compared to normal controls." (PMID 33172394, 2020). "α-Actinin-4 (ACTN4) is an actin-binding protein that belongs to the spectrin gene superfamily and acts as an oncogene in various cancer types." (PMID 33363146, 2020). "Recent findings suggested that ACTN4 affected the activity of NF-κB, thereby increasing the migration of cancer cells." (PMID 31766144, 2019). "A source of controversy on the role of ACTN4 in cancer stems from the fact that most of the clinical investigations use the IHC approach to evaluate ACTN4 expression." (PMID 31766144, 2019). "In line with this, investigation of ACTN4 protein partners will facilitate the development of anti-cancer compounds that directly interfere with these tumor-promoting protein-protein interactions." (PMID 31766144, 2019). "Anecdotally, the initial studies on the involvement of ACTN4 in the tumor growth showed that the over-expression of ACTN4 exhibited tumor suppressive activity in cancer cells." (PMID 31766144, 2019). "Since EMT reportedly confers multiple drug resistance to cancer cells, it is important to note that the over-expression of ACTN4 was noticed to parallel the accretion of drug resistance in several cancer cell lines." (PMID 31766144, 2019). "Generally, ACTN4 over-expression induces invasive phenotypes in most of the cancer cell lines studied, whereas ACTN4 knockdown decreases this pathophysiological manifestation." (PMID 31766144, 2019). "Taken together, this information highlights the importance of ACTN4 in the regulation of dissemination and proliferation of cancer cells." (PMID 31766144, 2019). "The study of special types of membrane protrusions called invadopodia showed that the knockdown of ACTN4 resulted in the disruption of these structures in cancer cells." (PMID 31766144, 2019). "It has been demonstrated that changes in the ACTN4 gene expression level affect the formation of structures responsible for cancer cell motility." (PMID 31766144, 2019). "Among candidate TRIP13-interacting partners, we selected ACTN4 for further investigation as prior reports showed that it is involved in cancer cell EMT and AKT signaling." (PMID 31533816, 2019). "The metastatic regulated function of ACTN4 were assessed by cancer stem cells (CSCs)-related assays, including mammosphere formation, tumorigenic ability, reattachment differentiation, and signaling pathway analysis." (PMID 29197410, 2017). "We demonstrated that overexpression of ACTN4 leads to an aggressively malignant phenotype of cancer cells with metastatic potential." (PMID 27121206, 2016). "We originally identified ACTN4 as a metastasis-related gene in cancer in 1998 and have investigated the biological mechanisms and clinical implications of actinin-4 in cancer metastasis." (PMID 26288717, 2015). "If ACTN4 protein levels are elevated, for example, due to copy number variations in cancer cells, the focal complexes consequently become predominantly occupied by ACTN4." (PMID 25860875, 2015). "This will reveal the precise contribution of each isoform in focal adhesion formation and the relevance of elevated levels of ACTN4 in cancer cells." (PMID 25860875, 2015).
cancer (continued). "ACTN4 failure to bind to ZYX closely associates with cancer pathogenesis, because compromised cell-substratum adhesion frequently leads to increased cancer cell motility and invasiveness." (PMID 25860875, 2015). "Among normal tissues and various cancer cell lines, we observed expression of ACTN4-SpEx8 only in a SCLC cell line and normal testis." (PMID 26288717, 2015). "Histological analyses of cancer tissues showed a strong correlation between ACTN4 expression and tumorigenesis in several types of cancers." (PMID 25632391, 2015). "Among these four actinin isoforms, α-actinin-4 (ACTN4), first cloned by Yamada's group, has been shown to play a crucial role in cancer invasion and metastasis and in maintaining normal kidney functions." (PMID 21085685, 2010). "Although the identify of amino acids between α-actinin-1 and α-actinin-4 is 87%, these two isoforms are reported to play contrasting roles in cancer cell survival and the effect of ACTN4 shRNA on cell growth even depends on the cell type." (PMID 21085685, 2010). "Despite the accumulating evidence of increased α-actinin-4 levels as a biomarker for cancer invasion and metastasis, the actual cellular functions of ACTN4 remain undetermined." (PMID 21085685, 2010). "Recent research has shown that levels of ACTN4 are elevated in various cancers, including CC." (PMID 41148856, 2025). "ACTN4 facilitates the migration of a wide range of cancer cells, leading to adverse outcomes, including colorectal cancer, intrahepatic cholangio-carcinoma, lung cancer, glioblastoma, pancreatic cancer, cervical cancer, melanoma, prostate cancer, gastric cancer, and ovarian cancer." (PMID 38739940, 2024). "Additionally, ACTN4 is involved in the radiation resistance of cancer cells and resistance to certain drugs." (PMID 38739940, 2024). "The actin-binding protein ACTN4, part of the actin-binding protein family and a non-muscle α-actin, has long been linked to cancer development." (PMID 39329952, 2024). "Downregulation of ACTN4 expression inhibited cancer cell growth, indicating that sEV ACTN4 may be a prognostic marker for evaluating tumor burden." (PMID 38093355, 2023). "Moreover, it was found that a higher frequency of metastasis, an aggressiveness of cancer, and shorter overall survival rates were all significantly correlated with increased ACTN4 activity." (PMID 38107139, 2023). "Previous studies have shown that ACTN4 is involved in the ERK signaling pathway in cancer cells." (PMID 37626047, 2023). "Increased expression of ACTN4 protein and ACTN4 gene amplification may be indicators of cancer invasive ability and metastatic ability in all patients with NSCLC." (PMID 36139525, 2022). "ACTN4 is an actin-binding protein that plays a key role in the movement of cancer cells." (PMID 35042862, 2022). "Actinin-4 (ACTN4) is an anti-binding protein involved in cancer invasion and metastasis." (PMID 36139525, 2022). "There are a number of studies investigating the effects of ACTN4 on cancer development." (PMID 36476259, 2022). "These preclinical studies suggest that ACTN4 may indicate the metastatic ability and malignancy of cancer." (PMID 36139525, 2022). "ACTN4 contributes to aggressiveness and metastasis of various cancers; therefore, we investigated whether ACTN4 plays a role in the progression of PCa." (PMID 33363146, 2020). "However, the correlation between the ACTN4 gene dosage and different cancer characteristics varies between studies." (PMID 31766144, 2019). "Taking into account the experimental data, the authors proposed that the therapy might impair metastatic activity of cancer cells with high ACTN4 expression." (PMID 31766144, 2019). "Consequently, such opposing findings can create difficulties in the extrapolation of published data to other types of well-characterized cancer models, and herein we review the evidence and mechanisms for ACTN4 activity and its regulation proposed to date." (PMID 31766144, 2019).
cancer (continued). "Apparently, ACTN4 may play opposing roles in cancer development and progression and its effect is strictly cell type and tissue specific." (PMID 31766144, 2019). "Taken together, the clinical and experimental data presented herein clearly suggest that ACTN4 expression levels may alter the migration ability and invasive potential of different cancer cells." (PMID 31766144, 2019). "Collectively, it is plausible that ACTN4 may affect drug resistance by attenuating apoptosis in cancer cells." (PMID 31766144, 2019). "Indeed, ACTN4 was shown to co-localize with invadopodia markers (ortactin, dynamin II, and phosphotyrosine) in cancer cell lines of various origin, such as MDA-MB-231, RPMI7951, DLD-1, and SCC61." (PMID 31766144, 2019). "The actin-binding protein ACTN4 belongs to a family of actin-binding proteins and is a non-muscle alpha-actinin that has long been associated with cancer development." (PMID 31766144, 2019). "However, a serious consideration for pharmacological targeting ACTN4 requires an in-depth evaluation of its activity in each type of cancer cell." (PMID 31766144, 2019). "Inhibition of ACTN4 function appears to attenuate cancer metastasis." (PMID 30061793, 2018). "In other words, ACTN4 is one of the most abundant and important targets of EA in breast CSCs, and this is not to exclude the existence of any other possible targets of EA in cancer cells." (PMID 29197410, 2017). "In general, ACTN4 is a prognostic biomarker for several kinds of cancers." (PMID 27121206, 2016). "Actinin, alpha 4 (ACTN4), a nonmuscle cytoskeleton protein, has been frequently reported to be associated with cell motility and cancer metastasis." (PMID 25885339, 2015). "ACTN4 is a critical gene related to actin cytoskeleton regulation and has been reported by multiple studies to play an important role in cell adhesion, cell motility, and cancer metastasis." (PMID 25885339, 2015). "Among ACTNs, ACTN4 is primarily involved in cell motility and cancer invasion." (PMID 25860875, 2015). "Furthermore, upregulated ACTN4 in cancer cells has been suggested as a biomarker for drug resistance and malignant cell invasion." (PMID 25632391, 2015). "Recently, ACTN4 was reported to enhance cancer cell motility, invasion, and metastasis." (PMID 25860875, 2015). "Therefore, we considered that CNI of ACTN4 more strictly predicted the vascular invasion of cancer cells and poor prognosis than protein expression of actinin-4." (PMID 24574362, 2014). "Thus, ACTN4 is essential in the cancer-promoting process of MINDY2." (PMID 37207150, 2023). "Thus, we are the first to demonstrate that ACTN4 may influence the resistance of cancer cells to the topoisomerase II inhibitors, and affect the efficiency of the DNA double strand breaks repair." (PMID 36476259, 2022). "ACTN4 encodes a nonmuscle, alpha-actinin isoform that is concentrated in the cytoplasm; participates in metastatic processes; and facilitates the motility, invasion, and metastasis of cancer cells." (PMID 30155352, 2018). "We next explored whether the anti-cancer and anti-metastasis effects of EA were ACTN4-dependant." (PMID 29197410, 2017). "This phenomenon could be explained by the fact that ACTN4 is involved in the formation of the cellular processes that are associated with cancer invasion, but is not involved in cell proliferation or in adhesion to endothelial cells." (PMID 27121206, 2016). "Furthermore, ACTN4 protein expression is closely related to poor outcome in patients with breast, colorectal, pancreatic, ovarian, bladder, and lung cancer." (PMID 25860875, 2015). "For example, protein actinin alpha 4 (ACTN4), is involved in the crosslinking of actin filaments thereby affecting F‐actin dynamics and migration ability of cancer cells." (PMID 39417309, 2025). "In conclusion, our study highlights the potential of ACTB, ACTN4, INF2, and MYL6 as therapeutic targets and biomarkers for PD and cancer." (PMID 39329952, 2024).
cancer (continued). "This study found that ACTB, ACTN4, INF2, and MYL6 are closely related to PD and pan-cancer and can be used as candidate genes for the diagnosis, prognosis, and therapeutic biomarkers of neurodegenerative diseases and cancers." (PMID 39329952, 2024). "In pan-cancer, the high expression of ACTB, ACTN4, and MYL6 in GBMLGG, LGG, MESO, and LAML had a poor prognosis, and the high expression of INF2 in LIHC, LUAD, UVM, HNSC, GBM, LAML, and KIPAN had a poor prognosis." (PMID 39329952, 2024). "To further investigate the cancer-promoting mechanism of MINDY2 in PC, we identified ACTN4 as an interacting protein of MINDY2 by immunoprecipitation, mass spectrometry, and immunofluorescence co-localization." (PMID 37207150, 2023). "Interestingly, the authors found that NF-kappaB and ACTN4 form a positive feed-forward loop whereby RelA transcriptionally up-regulates the ACTN4 gene, whose product in turn further activates NF- κB, resulting in enhanced survival, proliferation, and anchorage-independent growth of cancer cells." (PMID 31766144, 2019). "ACTN4 influences the cell cycle and cell motility and plays a key role in the development and spread of cancer, and some studies have shown that ACTN4 behaves differently in endometriotic lesions than in the normal endometrium." (PMID 39931061, 2025). "We examined the expression of ACTN4 in cancer tissues and adjacent non-tumor tissues in OS cases by RT-qPCR." (PMID 30879239, 2020). "Although further studies are needed to characterize the molecular mechanism of CRPC transition and PCa progression, our findings suggest that ACTN4 is involved in advancement of the EMT potential of PCa cells and acquisition of the aggressive cancer properties." (PMID 33363146, 2020). "Further experiments are required to decipher the molecular mechanisms that ACTN4 engages to promote EMT, metastases, and proliferation of cancer cells as well as developing precise therapies that will target the oncogenic features of ACTN4 while sparing its functions in normal cells." (PMID 31766144, 2019). "Especially, α-Actinins 4 (ACTN4), expressed in non-muscle cells, could enhance cancer cell migration and invasion." (PMID 27874083, 2016). "However, the reason why ACTN4, rather than ACTN1, is frequently associated with cancer malignancies despite similarities in domain structure, actin-binding and-crosslinking activities, and Ca2+-sensitivity between the two remains to be elucidated." (PMID 25860875, 2015). "Our investigation revealed new aspects of ACTN4 functions in human cells, since the involvement of ACTN4 in the DSB repair process and, consequently, modulation of cancer cell resistance to genotoxic drugs have not yet been described." (PMID 36476259, 2022). "Because the CYP2A6 locus in the 19q13 region is separated from the SPINT2 and ACTN4 loci by many genes, CYP2A6 amplification in human cancer has not been shown." (PMID 27902773, 2016).